POSTN (periostin)
Diseases named in the same sentence as POSTN in open-access papers (continued):
Sharing a sentence is not in itself a finding about the gene and the disease.
tumor (continued). "In addition, we could show that SMA and Periostin are significantly more frequently detectable in tissues with a high CK6 tumor expression." (PMID 36971797, 2023). "Although POSTN itself could not induce EMT evaluated by morphology and loss of E‐cadherin (data not shown), POSTN may promote tumor progression via p‐EMT program under TGF‐β signaling pathway." (PMID 36691359, 2023). "Furthermore, periostin plays a role in remodeling of the tumor microenvironment." (PMID 36691359, 2023). "The results of the study elucidated for the first time how periostin is the key protein secreted in TNBCs in response to the adipocyte–regulated tumor microenvironment, while periostin–neutralizing antibodies may serve as potential therapeutic agents in relation to TNBC progression." (PMID 37716956, 2023). "Yet, whether Periostin is necessary for tumor promotion in vivo is unknown." (PMID 38139195, 2023). "POSTN (periostin) may regulate multiple biological behaviors of tumor cells." (PMID 37240298, 2023). "In addition to binding to integrins, POSTN can also affect the TME to promote tumor metastasis." (PMID 37143134, 2023). "Besides, POSTN upregulation was detected in the tumour tissues of other cancers, consistent with previous reports on POSTN overexpression in a variety of human malignancies, suggesting that POSTN might serve as a common marker for tumour malignant potential." (PMID 38115703, 2023). "Our data suggest that FASN, which is important for catalyzing fatty acid synthesis in cancer, is functionally responding to the elevated levels of periostin in the tumor microenvironment, and that the increased expression of FASN in cancer cells may lead to increased fatty acid synthesis." (PMID 38049490, 2023). "Together, our results suggested that POSTN+ CAFs and SPP1+ macrophages were closely associated at the tumour stroma, which may be critical in inhibiting tumour immunity and promoting tumour progression, and targeting these cells may enhance the efficacies of ICI immunotherapies in NSCLC." (PMID 38115703, 2023). "However, four tumor markers (POSTN, pSMAD2/3, CXCL14, ADH1B, FAP) that have previously been reported to predict suboptimal debulking were selected in our model, although only p-SMAD2/3 was in the same direction but with lower discriminatory performance compared to prior reports." (PMID 36761962, 2023). "However, these inflammatory infiltrates were never associated with a variation in POSTN expression compared to the remaining tumor stroma." (PMID 38076555, 2023). "Collectively, our data provided new insights on the characteristics and functions of CAF subtypes in NSCLC and suggested the critical roles of POSTN+ CAFs in immune suppression and tumour progression, indicating that they may be promising targets for the treatment of NSCLC." (PMID 38115703, 2023). "In addition, overexpressing POSTN in DDR2-depleted CAFs led to an increase in tumor cell invasion." (PMID 35884543, 2022). "The most relevant studies investigating periostin in PCa, which were mainly focused on assessing the correlation between periostin expression, tumor grade, and patient outcome, showed contradictory results and missed to clearly define the identity of periostin-expressing cells within the tumor mass." (PMID 35887333, 2022). "POSTN production might be induced by several tumor-derived factors including TGF-β." (PMID 35567669, 2022). "The diagnostic values of anti-POSTN and anti-TIMP1 autoantibodies in ESCC patients of different clinicopathological characteristics, including lymphatic metastasis, distance metastasis, differentiation, TNM stage, family tumor history, gender, and age, were further explored." (PMID 35559040, 2022). "Interestingly, periostin could also be delivered to metastatic sites by tumor exosomes, thereby promoting metastasis by priming PMN of the target tissue before tumor cell entrance." (PMID 36224629, 2022).
tumor (continued). "Furthermore, POSTN exerts a vital role in the communication between tumour cells and the surrounding microenvironments, thereby promoting the process of establish and remodel the tumour microenvironment (TME)." (PMID 35508298, 2022). "All these common gene hubs are ECM related proteins, which could be involved in the process of cancer cell proliferation, invasion and metastasis, showing that POSTN could regulate the microenvironment of tumor and exerted a significant role in cancer development, especially in LUSC." (PMID 35508298, 2022). "In addition, these data showed that GB-induced CMA in PCs also leads to the secretion of molecules that can promote pro-tumor immune responses, such as gelsolin, periostin, and osteopontin, supporting previous data showing the contribution of the PC secretome to GB immune evasion." (PMID 36012149, 2022). "Notably, since POSTN stimulates TAMs to produce various chemokines and MMPs that might be correlated with tumor progression, POSTN can be a target for immune therapy in the future." (PMID 35409404, 2022). "However, it is known that endothelial cells will downregulate TSP1 and upregulate factors such as TGF-β, periostin and fibronectin, which may promote tumor cell survival and facilitate additional production of tumor-derived angiogenic factors." (PMID 33805598, 2021). "However, whether periostin expression in activated fibroblasts of IPF is involved in the tumor progression of LC-IPF remains unclear." (PMID 34702952, 2021). "Similarly, CAF-secreted POSTN may also promote tumor progression in CRC through YAP/TAZ activation in cancer cells." (PMID 33553157, 2020). "Periostin could be detected both in cancer cells and in the tumor stroma." (PMID 31936272, 2020). "Our investigation suggests that POSTN may facilitate tumor progression in multiple ways." (PMID 33083453, 2020). "We believe no previous studies have shown a positive significant correlation of POSTN in tumour stromal cells with D2-40 (CAFs) in NSCLC as well as in the AC and SCC subtypes, a correlation that may suggest the association of POSTN with CAF cells in tumour stroma." (PMID 32987711, 2020). "Moreover, there was an inverse correlation between POSTN expression and tumor stage." (PMID 32467737, 2020). "Moreover, in vitro periostin knock-down experiments demonstrate reduced tumor migration and invasion, in model systems, thus EV periostin maybe also functionally important in tumor progression." (PMID 30895170, 2019). "Tumor cells may escape apoptosis through periostin-activated Akt/PKB pathway in hypoxia." (PMID 31440236, 2019). "In contrast to previous studies focusing on the changes of HCC cells response to heat treatment, we provide a new evidence that activated HSCs enriched in tumor-promoting microenvironment could promote the accelerated progression of heat-treated residual HCC through POSTN secretion." (PMID 30400797, 2018). "The exact mechanism of how periostin leads to mesenchymal tumor cell expansion is unknown." (PMID 29507310, 2018). "Additionally, CATB (Cathepsin B) was previously reported as a potential candidate cancer biomarker in HCC, HPT (haptoglobin) was reported to associate with tumor progression in HCC, while POSTN (periostin) was reported as a marker for malignant transformation of hepatocytes." (PMID 30598095, 2018). "Considering these observations, we first examined the expression of mouse and human periostin variants in MCF10DCIS tumor with or without chemotherapy using variant-specific primer sets and found that hPN2-1 and hPN2-2 were the most dominant variants after PTX-treatment." (PMID 29507310, 2018). "Stroma-derived periostin (POSTN), a component of the extracellular matrix within the secondary sites lung is shown to recruit Wnt ligands and thereby increases Wnt signaling, which enables cancer stem cell maintenance and thus promotes tumor colonization and metastasis." (PMID 29197379, 2017).
tumor (continued). "Healthy bladders express periostin in a belt of stroma immediately adjacent to the urothelium, and it may be that the appearance of periostin in MIBC urinary EVs is the result of tumor invasion into the stroma which allows stroma-derived periostin to access the bladder lumen." (PMID 26981774, 2016). "Following tumor resection, six out of six NMIBC patients had urinary EV periostin levels indistinguishable from healthy controls, and four patients retaining stage pT1 NMIBC tumors had significantly higher levels, suggesting that periostin might be a sensitive marker of tumor recurrence." (PMID 26981774, 2016). "Besides promoting tumor progress, our data indicated that the induced-POSTN might be involved in the local engraftment of metastatic HNC cells." (PMID 26857387, 2016). "Moreover, knockdown of POSTN in PaC cells reduced tumor growth and VEGF expression in vivo." (PMID 27223086, 2016). "We therefore examined whether the tumour-promoting effects of CAFs are modulated through periostin." (PMID 25345775, 2015). "Moreover, the attenuated metastatic potential was associated with decreases in both CD24+CD90+ CSC-enriched cancer cell proportions and mammosphere formation, and the addition of POSTN reversed the decreased mammosphere formation in MMTV-PyMT POSTN−/− tumour cells." (PMID 24216702, 2013). "Therefore, targeting POSTN and other extracellular matrix components of tumor microenvironment may help to develop new therapeutical strategies to inhibit tumor metastasis." (PMID 24009721, 2013). "Likewise, myofibroblast-derived factors have been shown to impose the CSC phenotype by promoting Wnt signaling in tumor cells and periostin, a component of the extracellular matrix, promotes the stemness of cancer cells and increases their ability to form metastasis by upregulating Wnt signaling." (PMID 23029025, 2012). "Periostin secreted by tumor cells acts in a paracrine manner to augment the survival of endothelial cells and induces neovascularization, consistent with the notion that enhanced survival of intratumoral endothelial cells is critical for successful tumor angiogenesis." (PMID 22952986, 2012). "Besides, Periostin always plays a great role in tumor invasion and metastasis." (PMID 21714934, 2011). "Scientific reports have shown that POSTN and PDPN proteins play an important role in the carcinogenesis of various types of neoplasms in both humans and animals." (PMID 41361308, 2025). "In this study, we aimed to clarify the clinicopathologic significance of periostin and Smad2/3 expression in CRC, with a particular focus on the tumor microenvironment." (PMID 39941916, 2025). "Tumor area activated various proliferation and metastasis-related signaling pathways (MK, SPP1, SEMA3, MIF, VEGF, PERIOSTIN, and PDGF) and immunosuppression-related signaling pathway (GALECTIN)." (PMID 39670859, 2025). "Employing Dox-inducible POSTN knockdown in SCLC and NOTCH1 functional inhibitor DAPT in fibroblasts effectively improved the anti-tumor efficacy, offering a novel therapeutic strategy to impede SCLC liver metastasis." (PMID 39762921, 2025). "Periostin (POSTN) is located in the extracellular matrix (ECM) and triggers tumor growth signals by binding to integrin receptors." (PMID 41018265, 2025). "SMA, PDGFRB, SDF1, POSTN, and DCN were also found in fibroblast-like cells within the connective tissue septa separating tumor cell nests, with POSTN and DCN occasionally present at the bone surface (data not shown)." (PMID 40841830, 2025). "These cells are recruited by GSC-induced periostin secretion, meaning that silencing periostin can be considered another valid alternative to target the TME and alter the tumor proliferation." (PMID 40944840, 2025). "The primary function of CAFs is to shape the tumor microenvironment by secreting ECM proteins, such as periostin, and metabolic factors, thereby enhancing cancer cell survival and migratory capacity." (PMID 39941916, 2025).
tumor (continued). "In view of this, jointly targeting the POSTN-integrin and the AKT/mTOR signaling pathway can synergically disrupt the tumor-promoting signaling network." (PMID 41018265, 2025). "Periostin induces the activation of FAK-Src kinases through integrin-mediated signaling, resulting in YAP/TAZ activation and subsequent IL-6 expression in tumor cells." (PMID 39936032, 2025). "POSTN activates PI3K/Akt and MAPK/ERK signalling pathways, regulates cell growth and metastasis, and shapes the tumour microenvironment." (PMID 40038875, 2025). "The POSTN-integrin interaction is central to HCC progression, influencing several downstream signaling pathways that support tumor development." (PMID 41018265, 2025). "PPI analysis revealed COL10A1, POSTN, SPP1, MMP11, and GREM1 as key hub genes in extracellular matrix (ECM) remodeling and tumor progression." (PMID 40826767, 2025). "In contrast, stromal CAFs exhibit increased expression of ECM components, such as POSTN and LUM, promoting tumor cell invasion and metastasis through ECM hardening." (PMID 41408647, 2025). "Further analyses revealed that ECM-remodeling fibroblasts can interact with epithelial cells through the POSTN-ITGAV/ITGB5 ligand-receptor axis, a critical pathway that promotes tumor progression." (PMID 40520021, 2025). "POSTN is secreted into the extracellular stroma to form ECM, creating a favorable microenvironment for tumor cell migration and invasion." (PMID 41018265, 2025). "Significant correlations between the expression of POSTN and PDPN and the number of positive cells and/or the intensity of the reaction were observed within each tumour type, as presented in the following paragraphs." (PMID 41361308, 2025). "POSTN is a multifunctional ECM protein related to clinical diagnosis, patient prognosis, tumor cell proliferation and invasion, immune regulation and angiogenesis in HCC patients." (PMID 41018265, 2025). "In comparison to tumor vasculature in MVP and CT regions, SLIT3, COL8A1, LUM and POSTN showed enhanced spatial enrichment within the GBM hyperplastic region." (PMID 41366031, 2025). "POSTN (Periostin), an ECM glycoprotein induced by TGF-β, emerged as one of the top hub genes and exemplifies the tumor–stroma crosstalk common to EAC and ESCC." (PMID 40872572, 2025). "This could be achieved using peptides or inhibitors that specifically inhibit POSTN-integrin binding, such as peptides targeting CD51 or selective γ-secretase inhibitor LY3039478, thereby attenuating the downstream signaling pathways associated with tumor growth." (PMID 41018265, 2025). "These three POSTN+ clusters represent myofibroblastic CAF (myoCAF) phenotypes that are prognostic and can promote tumour invasion in EAC." (PMID 40640495, 2025). "Among the various players in HCC, POSTN has garnered attention for its multifaceted role in tumor biology, particularly its involvement in the TME and signaling pathways that promote tumor growth, metastasis, and treatment resistance." (PMID 41018265, 2025). "The prominence of POSTN, SPARC, and TGFBI among the shared hubs also underscores the role of TGF-β pathway activity and a myofibroblastic stroma in both tumor types." (PMID 40872572, 2025). "To further elucidate the molecular mechanisms of POSTN-mediated EMT and tumor aggressiveness, we used scRNA-seq samples from the CRA001160 dataset." (PMID 40520021, 2025). "In summary, our results unveil POSTN as a key driver in SCLC growth and metastasis, contributing to a fibrosis-supportive phenotype in the tumor niche." (PMID 39762921, 2025). "Subsequent western blotting confirmed reduced expression of POSTN, Snail, and MMP9 in POSTN-knockdown xenograft tumor tissues, suggesting the inhibition of SCLC metastatic abilities through the downregulation of EMT-related genes." (PMID 39762921, 2025). "POSTN secreted from GSCs promotes GSC self-renewal and tumor growth via activation of the PI3K/AKT/β-catenin/FOSL1 pathway." (PMID 39227950, 2024).
tumor (continued). "Based on these results, we further focused on POSTN+ fibroblasts and SPP1+ macrophages and investigated how they interact with each other and how their cellular communication regulates tumor cells." (PMID 38519500, 2024). "Among nonmalignant cell types, RSPO1+ fibroblasts and FOLR2+ macrophages were identified as potential tumor-suppressing populations and POSTN+ fibroblasts and SPP1+ macrophages were identified as tumor-promoting populations." (PMID 38519500, 2024). "In this study, we showed that POSTN secreted from GSCs promotes GSC self-renewal and tumor growth via activation of the αVβ3/PI3K/AKT/β-catenin/FOSL1 pathway." (PMID 39227950, 2024). "Our findings revealed that POSTN secreted from GSCs promotes GSC self-renewal and tumor growth via activation of the αVβ3/PI3K/AKT/β-catenin/FOSL1 pathway." (PMID 39227950, 2024). "At sprouting endothelial tips, the tumor-suppressive properties of the microvascular endothelium are lost, and a decrease in TSP-1 and an increase in pro-tumoral ECM molecules, as periostin, are observed." (PMID 39682261, 2024). "An interesting discovery is that specific reciprocal communication occurs between POSTN+ fibroblasts and SPP1+ macrophages, with an upward trend in the interaction strength during tumor progression." (PMID 38519500, 2024). "HMGB2 in POSTN+ fibroblasts is predicted to bind to PLD2, LRP5, MYLK, and CD44 on tumor cells, regulating downstream genes, including BIRC5, CCNA2, CCNB1, CCNB2, CDC20, and MKI67, which are related to the cell cycle." (PMID 38519500, 2024). "Like those in POSTN+ fibroblasts, the number of SPP1+ macrophages in tumor tissues were dramatically increased, and higher infiltration correlated with a shorter overall survival in TCGA HNSCC patients." (PMID 38519500, 2024). "POSTN activates the PI3K/AKT/β-catenin/FOSL1 pathway in an autocrine manner to promote GSC self-renewal and tumor growth." (PMID 39227950, 2024). "CAF-derived periostin (POSTN) and versican (VCAN) play significant roles in CAF activation and tumor progression." (PMID 39200270, 2024). "Yumm1.7- POSTN+ and Yumm1.7-CTR cell lines were subcutaneously inoculated in mice and, 1 week later (day 0), POSTN+ and CTR tumor-bearing mice were treated with MEKi for 5 days." (PMID 38942020, 2024). "To further investigate how WNT and periostin influenced each other, we first treated ALK/MYCN tumor cells with the WNT inhibitor WNT-C59 at 10 μM for 48 h." (PMID 38451815, 2024). "We reveal the crucial role of CAF-derived POSTN and tumor cell-derived IL-4 in driving the development of papillary thyroid tumors through the POSTN-integrin-FAK-STAT3-IL-4 pathway in tumor cells and IL-4-STAT6-POSTN signaling in CAFs." (PMID 38773979, 2024). "Silencing POSTN in GSCs markedly reduced TAM density, inhibited tumor growth, and increased survival of mice bearing GSC-derived xenografts, confirming the importance of POSTN for GSC niche." (PMID 38347567, 2024). "Reciprocally, inhibition of the WNT pathway reduced expression of POSTN and growth of ALK/MYCN tumor cells." (PMID 38451815, 2024). "Following digital analysis, we divided the patient cohort according to median expression in tumor stroma (FAP: n = 106 low, n = 105 high; PDGFRb: n = 106 low, n = 106 high; periostin: n = 106 low, n = 105 high; α-SMA: n = 107 low, n = 106 high)." (PMID 38328551, 2024). "For example, TGFB3-SDC4 and INHBA-TGFBR3 were found between POSTN+ fibroblasts and tumor cells and CXCL5-BDKRB2 and CCL7-ACKR2 were found between SPP1+ macrophages and tumor cells." (PMID 38519500, 2024). "Western blot and qRT-PCR analyses showed that POSTN and CAF activation marker Acta2 expression were up-regulated in CAFs co-cultured with IHH-4 or TPC-1 tumor cells compared with CAFs cultured alone." (PMID 38773979, 2024). "On the other hand, in tumor matched 0923CAF after coculture with LK0923, the most evident changes were a significant decrease in both ACTA2 and POSTN and a strong increase of PDPN mRNA expression." (PMID 38822309, 2024).